ENSG00000283696 (novel transcript)
Gene: Long non-coding RNA gene on chromosome 1 (161,399,409 to 161,424,820, forward strand). Ensembl gene ENSG00000283696.
Gene Ontology:
Molecular function: triplet codon-amino acid adaptor activity
Biological process: translation